IL6 (interleukin 6)
Diseases named in the same sentence as IL6 in open-access papers (continued):
Sharing a sentence is not in itself a finding about the gene and the disease.
COVID-19 (continued). "Similarly in severe COVID-19 emerging evidences suggest a correlation between increased IL-6 levels and the need for invasive mechanical ventilation." (PMID 33505996, 2020). "The authors note that IL-6 is generally low in children, but it is high for a brief time in early childhood, which could explain the Kawasaki-like COVID-19 sequela in some children." (PMID 33014983, 2020). "Both complications occurred quite late after COVID-19 diagnosis and were probably precipitated by systemic inflammation, as indicated by a significant delayed increase in inflammatory markers, including interleukin-6 (IL-6)." (PMID 33339534, 2020). "Therefore, future research should be directed to the identification of responsible molecules that regulate the IL-6 amplifier in severe COVID-19, thereby enabling the development of new clinical interventions using small molecules against these targets." (PMID 33014208, 2020). "The elevations of IL-6 and IL-10 are highly consistent in COVID-19." (PMID 32754163, 2020). "If this is the case, the cytokine storm in severe COVID-19 could be inhibited by blockade of the IL-6 amplifier." (PMID 33014208, 2020). "Aside from direct virus-induced apoptosis, excessive release of cytokines observed in COVID-19 patients, e.g., IL-1β, IL-6, and IL-10, may lead to apoptosis in several cell types." (PMID 32854430, 2020). "Similarly, severe COVID-19 patients have higher concentrations of IL-2, IL-6, IL-8 and TNF in the serum than mild cases, suggesting that the magnitude of cytokine storm is associated with the severity of the disease." (PMID 32698440, 2020). "We propose that miR-146a rs2910164 GC through Notch-1 upregulation causes excessive secretion of IL-6 which may then affect cellular uptake of SARS-CoV-2, development of COVID-19, and contribute to the cytokine storm in patients." (PMID 33072191, 2020). "Furthermore, elevated levels of circulating IL-6 in a cohort of 150 patients in a recent retrospective study were found to be predictive of mortality in hospitalized COVID-19 patients." (PMID 32645974, 2020). "Like EVD, elevated IL-6 was found to be significantly correlated with death in COVID-19 patients, suggesting that patients with clinically severe SARS-CoV-2 infection might also have a CRS syndrome." (PMID 33071786, 2020). "Several studies showed that high IL-6 plasmatic levels were related to COVID-19 severity, suggesting that IL-6 inhibitors, like Tocilizumab, could be a potential therapy for severe COVID-19 patients." (PMID 32962761, 2020). "The forthcoming results of a phase III randomized controlled study sponsored by Hoffmann-La Roche (COVACTA, NCT04320615) may provide more valid clinical evidence and understanding of anti-IL-6 signaling agent usage in patients with COVID-19." (PMID 33384605, 2020). "One study illustrated the predictive ability of IL-6 for prognosis in patients with COVID-19." (PMID 33384605, 2020). "SARS-CoV-2 infection can lead to injury of multiple organs, it will be interesting to explore whether IL-6 in systemic circulation mediates other organ or tissue injury in COVID-19." (PMID 32727465, 2020). "Inflammatory cytokines such as TNF-α, interferon gamma (IFN-γ), interleukin 6 (IL-6), and IL-10 present in the plasma of COVID-19 patients induce mitochondrial reactive oxygen species production and impede mitochondrial oxidative phosphorylation and ATP production among other effects." (PMID 32854430, 2020). "Moreover, we observed that during COVID-19 evolution, levels of IL-6 seemed to be more stable in patients with headache compared to the ones without it." (PMID 33146036, 2020). "Even though inflammatory cytokine storms were thought to be a mechanism for COVID-19 progression, there was only an increase in IL-2, IL-4, IL-6, IL-10, TNF-α, and IFN-γ when comparing pneumonia patients with healthy people, but no significant increase in severe patients compared to mild patients." (PMID 32985562, 2020).
COVID-19 (continued). "Besides IL-1, increased levels of IL-6 have also been consistently reported in severe cases of COVID-19, with an impact on immune cell function and the anti-viral mechanisms of immune cells." (PMID 32599813, 2020). "Finally, how to achieve the optimal effect of anti-IL-6 signaling agents in patients with critical COVID-19 is still worth further study." (PMID 33384605, 2020). "IL-6 plays a central role in acute inflammation and cytokine storms, and increasing evidence suggests interference with IL-6 has a potential therapeutic effect in COVID-19." (PMID 33031060, 2020). "In summary, in combination with our results and prior reports, IL-6 may play a key role in triggering inflammatory storms in COVID-19 patients." (PMID 32669467, 2020). "Apart from IL-6 signaling, other pro-inflammatory pathways may also contribute to the development of COVID-19." (PMID 33195318, 2020). "Anti-inflammatory cytokine therapy like anti-IL-6 and administration of MSCs may have potential for supportively treating COVID-19." (PMID 32806722, 2020). "COVID-19 infects the upper and lower respiratory tract, causing the release of pro-inflammatory cytokines such as interleukin 1β (IL-1β), tumor necrosis factor (TNF), and IL-6." (PMID 32802622, 2020). "However, future clinical trials are needed to better understand the impact of tocilizumab interference with IL-6 and provide a therapeutic strategy for treatment of COVID-19." (PMID 33031060, 2020). "Drugs down-regulating the STING pathway either upstream (like aspirin and IVIgs, and Vitamin -D), or downstream (like IL-6 inhibitors or inhibitors of the JAK-STAT pathway) could be beneficial in COVID-19, and perhaps also in some KD." (PMID 32574107, 2020). "Interleukin-6 is an important driver of both clinical and inflammatory abnormalities of COVID-19." (PMID 33089038, 2020). "Anxiety is a psychosocial factor shown to associate with increased IL-6 levels independent of depressive symptoms, potentially further accelerating COVID-19 severity." (PMID 33134238, 2020). "Various clinical trials are currently under way using immunomodulatory IL-1 and IL-6 inhibitors or anti-IL-6R antibodies (anakinra, tocilizumab, siltuximab, and sarilumab) in patients with COVID-19 (COVID-19 Treatment Guidelines Panel, 2020); limited data, however, is yet available." (PMID 33692684, 2020). "Altogether, IL-6 may play multiple and possibly contrasting roles in patients with cancer and COVID-19, which will need to be addressed by future studies." (PMID 33194755, 2020). "Thus, the present study highlights the crucial role of IL-6 signaling in endothelial dysfunction during bacterial infection and COVID-19." (PMID 32826331, 2020). "Patients with severe COVID-19 have a higher IL-6/Interferon-γ ratio than those who present with a moderate disease, which could be related to the cytokine storm leading to lung injury." (PMID 32849623, 2020). "The observation of dynamic IL-6 levels also helps to confirm the COVID-19 response to treatment." (PMID 33031060, 2020). "Several IL-6 antagonists are being studied for safety and efficacy in COVID-19." (PMID 33059711, 2020). "A recent elegant study has identified unique immune signatures in severe COVID-19 patients, characterized by a high sustained cytokine production of interleukin-6 (IL-6), a pleiotropic cytokine with multiple effects in these patients, distinct from patients with bacterial sepsis." (PMID 32848893, 2020). "Moreover, COVID-19 patients appear to be in a hyper inflammation state or cytokine storm like condition, which resulted in secretion of high interleukin-6 (IL-6) levels, which in turn translates to hyperviscosity and increases the risk for stroke propensity." (PMID 33123082, 2020). "Univariate analysis showed that the erythrocyte count, hemoglobin count, neutrophil count, lactate dehydrogenase, CK-MB, troponin I, procalcitonin, CRP, IL-6, and IL-10 may be factors that affect the severity of COVID-19." (PMID 33192519, 2020).
COVID-19 (continued). "Treatments currently in use or in the final stages of clinical development include: Remdesivir (GS-5734), a Lopinavir/Ritonavir association (with or without Interferon 1ß), HCQ, anti-IL-6, Jakinibs or intravenous immunoglobulin are evaluated to treat COVID-19." (PMID 32933031, 2020). "Retrospective cohort studies: IL-6 inhibitors in the treatment of patients with COVID-19." (PMID 32982743, 2020). "In line with this evidence, IL-6 inhibition may be beneficial also for cardiovascular thrombotic complications occurring in patients with COVID-19." (PMID 32655577, 2020). "Additionally, an increase of IL-6 levels predicts adverse outcomes of COVID-19, underscoring inflammaging as the main ally of SARS-CoV-2." (PMID 32991323, 2020). "The binding of COVID-19 to TLRs activates the formation of active IL-1β and IL-6." (PMID 32695683, 2020). "IL-6 has an essential part in inflammatory cytokine storm in COVID-19." (PMID 33059757, 2020). "Additionally, IL-17 is positively regulated by IL-6 which is significantly increased in serious states of COVID-19, adding to the fatal cytokine storm." (PMID 33510644, 2020). "In addition, among these cytokines, interleukin-6 (IL-6) is an important member of pro-inflammatory cytokines, which is positively correlated with the severity of COVID-19 symptoms." (PMID 33519677, 2020). "The identification of host factors driving the severe pathogenic processes in the lung, such as the role of macrophages and IL-6 in driving lung damage, may provide critical insight into the molecular and cellular determinates of COVID-19 pathogenesis." (PMID 32841215, 2020). "Cytokine storm pathophysiology in CoViD-19 is often reported to be due to high levels of IL-6 in individuals, although this, we believe, could synergize with TNF-α and IL-1β levels." (PMID 32574269, 2020). "Among detected cytokines, IL-6 appears to be the most significantly involved in COVID-19 progress." (PMID 32916812, 2020). "Although IL-6 is indicated as a biomarker in predicting severe status of COVID-19 patients, IL-8 is an easily detectible and sensitive biomarker in either mild or severe COVID-19 patients." (PMID 33488599, 2020). "Future investigations will be essential to clarify whether IL-6, IL-1β, and other pro-inflammatory cytokines produced during COVID-19 may affect tumor cells and the TME, possibly supporting the use of anti-cytokine therapies in cancer patients with COVID-19." (PMID 33194755, 2020). "A high dose of vitamin B6 administration may reduce the TNF-α, IL-6, and D-dimer levels and improves endothelial integrity along with preventing coagulopathy in COVID-19 patients." (PMID 33195370, 2020). "(Zhigancao)] with conventional western medicine to treat 40 patients with ordinary COVID-19, and found that after three days of treatment, IL-6 level significantly decreased compared with that before the treatment (p<0.05), and levels of AST, ALT and creatinine were normal." (PMID 33192523, 2020). "IL-6 inhibitors, which alleviate severe inflammation induced by cytokine release after viral infection, may improve clinical outcome of critical cases of COVID-19." (PMID 33364959, 2020). "Moreover, as a consequence of higher Ang II levels, an increase in systemic cytokines, especially interleukin-6 (IL-6), has been observed in subjects with COVID-19." (PMID 33203141, 2020). "In conclusion, this study compared the clinical characteristics between critical and non-critical COVID-19 inpatients, and qSOFA score and elevation of IL-6 are risk factors for critical condition." (PMID 33067568, 2020). "Notably, expression of interleukin (IL)-6 was unchanged in the lungs of patients with COVID-19, a finding that raises a question about the potential for anti-IL-6 therapy to help resolve the pulmonary inflammatory process in patients with severe disease." (PMID 33082228, 2020).
COVID-19 (continued). "Also, that IL-6, IL-10 and interferon-gamma that are elevated in KD as well as in COVID-19, where these are shown to exert an inflammatory-mediated lung injury." (PMID 33162899, 2020). "In critically ill COVID-19 patients a cytokine storm with highly elevated IL-6 has been described." (PMID 33679725, 2020). "Indeed, some studies have shown that both lymphopenia and increased interleukin-6 blood level were prognosis factors in COVID-19 patients." (PMID 33363190, 2020). "Higher blood concentrations of IL-6 were reported to be predictive of fatal outcome in COVID-19 patients therefore blocking IL-6 using antibodies may be effective." (PMID 34192268, 2020). "Since IL-6 is a functional marker of cellular senescence, the age-dependent enhancement of the IL-6 Amp might correspond to the age-dependent increase in COVID-19 mortality." (PMID 32983152, 2020). "Individually, laboratory abnormalities have been reported in COVID-19 patients, including an elevation of inflammatory markers and liver enzymes, abnormal renal function tests, and an elevated serum soluble interleukin 2 (IL-2) receptor (sIL2R) and IL-6." (PMID 32957548, 2020). "In COVID-19 patients, levels of IL-6 seem directly correlated with the severity of the disease." (PMID 32546188, 2020). "Introduction/objectives: An interleukin-6 inhibition strategy could be effective in selected COVID-19 patients." (PMID 33304913, 2020). "Whether tocilizumab can restore T cell counts in COVID-19 patients by suppressing IL-6 signaling remains uninvestigated." (PMID 32425950, 2020). "Elevated levels of IL-6, which appears to be from myeloid cells in COVID-19 patients, could predict the severity of the disease and the need for intensive care." (PMID 33425951, 2020). "IL-6 amplification may contribute to the hyperinflammation observed in COVID-19 similar as seen in multiple inflammatory and autoimmune diseases." (PMID 32961074, 2020). "In summary, IL-6 blockade may be a useful option in COVID-19 when administered early to those with signs of excessive inflammation." (PMID 33154972, 2020). "The evidence presented included age-stratified IL-6 concentrations from a healthy Italian population were highly correlated with age-stratified Italian COVID-19 deaths, which in turn were highly correlated with age-stratified COVID-19 death rates in the UK." (PMID 33142828, 2020). "Besides IL-6, also IL-1β has been reported to be elevated in COVID-19 patients as compared to controls." (PMID 33194755, 2020). "Moreover, IL-6 blood measurement has been pointed out as a potential biomarker of COVID-19 severity." (PMID 33391152, 2020). "COVID-19 patients also show IL-6-mediated low HLA-DR expression and lymphopenia." (PMID 32848893, 2020). "Notably, both an increase in CRP and IL-6 and a decrease in lymphocytes were common in COVID-19 patient sera." (PMID 33195363, 2020). "In line with this hypothesis, a longitudinal study showed that IL-6 increases late during the COVID-19 progression." (PMID 32708755, 2020). "Accordingly, levels of IL-6 are similarly increased in the hyperinflammatory phenotype of non-COVID-19 ARDS irrespective of its causative mechanism, but interventions targeting single cytokines in this setting have a long history of failure." (PMID 33123149, 2020). "In a recent retrospective multi-center study of 150 confirmed COVID-19 cases in Wuhan, China, elevated ferritin and IL-6 were found as predictors of lethality, suggesting that mortality might be due to virally-driven hyperinflammation." (PMID 32933031, 2020). "High levels of IL6 and CXCL8 are associated with severe cases of COVID-19 pathogenesis." (PMID 33362771, 2020). "The secretion of TNF-α and IL-6 by CD4+ Th cells in the peripheral blood may not be the main reason for the significant increase in TNF-α and IL-6 in the peripheral blood of COVID-19 patients." (PMID 32976531, 2020).
COVID-19 (continued). "As a result, concomitant use of steroids along with Remdesivir may lead to lower drug levels of Remdesivir in COVID-19 patients with severe inflammation, and therefore higher IL-6." (PMID 32708430, 2020). "IL-6 has been suggested as a potential prognostic marker of COVID-19 disease severity." (PMID 32256705, 2020). "Elevated levels of inflammatory cytokines, especially interleukin-6 (IL-6), have been reported in patients with COVID-19, and, for this reason, anti-inflammatory therapies, such as IL-6 blockers and interleukin-1 blockers (IL- 1β) are beeing tried as a treatment." (PMID 32690985, 2020). "Therefore, the levels of CRP, ESR, IL-6, ferritin, procalcitonin, and lactate dehydrogenase can serve as potential markers for the evaluation of COVID-19 prognosis." (PMID 33163160, 2020). "In combination with a separate study, which reported that patients with severe cases of COVID-19 showed increases in IL-6 and IFN-γ, we propose the hypothesis that IL-6 and IFN-γ can be independent predictors for rehabilitation efficacy." (PMID 33274223, 2020). "Moreover, it has been observed that COVID-19 induces high levels of IL-6 for at least 2 weeks after disease onset." (PMID 32256705, 2020). "Therapeutic modulation of IL-6 may therefore be particularly relevant to patients with cancer and COVID-19." (PMID 33330085, 2020). "IL-6 is also a predictor of mortality for COVID-19 patients in ICU." (PMID 33505321, 2020). "The levels of IL-6 and IL-10 were higher in severe COVID-19 compared with that in active AOSD." (PMID 33552062, 2020). "The high levels of IL-6 and IL-8 observed here indicate that tocilizumab and siltuximab may be particularly effective for treating hospitalized pediatric and female patients with COVID-19." (PMID 41313205, 2026). "Finally, evolving COVID-19 treatment strategies—including corticosteroids, IL-6 inhibitors, ventilation practices, and anticoagulation—may have independently influenced outcomes, complicating isolation of infection-specific mortality effects." (PMID 41597404, 2026). "Reducing the activity of the IL-6 signaling pathway might help prevent COVID-19." (PMID 40895261, 2025). "Interestingly, as observed in human COVID-19 patients with fatal disease (KO and 1A0) and those with severe disease (6A4) had overall, significantly increased systemic levels of G-CSF, IL-6, IL-10, TNF-α, IL-12 (p40), IL-17A, CCL5, and CCL11 compared to those with moderate disease (6A2 and 1A3)." (PMID 40242753, 2025). "Another key growth factor TGFβ that stimulate pulmonary fibrosis during COVID-19 acute lung injury are produced due to JAK1-STAT1 dysregulation led hyperactivation of STAT3 which is a key transcription factor for the overexpression of harmful IL-6 that stimulates transforming growth factor-1beta." (PMID 40410684, 2025). "In addition, according to a literature-based pathway, anxiety may upregulate multiple cytokines (IL6, IL10, and TNF) and angiotensin II, which are associated with harmful effects during COVID-19." (PMID 40766923, 2025). "In the context of COVID-19, kefir demonstrated antimicrobial and immunomodulatory activity by downregulating the expression of pro-inflammatory cytokines such as interleukin-6 (IL-6), interleukin-1 (IL-1), tumor necrosis factor-alpha (TNF-α), and interferon-gamma (IFN-γ)." (PMID 40647113, 2025). "Moreover, IL-6 levels predicted troponin elevation (β = 1.40 ng/L per pg/mL, p = 0.002, R2 = 0.21), indicating a potential mechanistic link between inflammation and cardiac injury in COVID-19-related sepsis." (PMID 41012595, 2025). "IL-6, a key driver of hyperinflammation, has been targeted with IL-6 inhibitors such as tocilizumab and sarilumab, which have demonstrated efficacy in acute COVID-19 but may also have a role in managing persistent post-COVID-19 inflammatory syndromes." (PMID 40094929, 2025). "However, it was demonstrated that administration of an anti-IL-6 blockade during acute severe COVID-19 could normalize the persistent phenotypes." (PMID 41226415, 2025).